CCT4 (chaperonin containing TCP1 subunit 4)
Diseases named in the same sentence as CCT4 in open-access papers (continued):
Sharing a sentence is not in itself a finding about the gene and the disease.
cancer (20 papers, 2019 to 2025). A tumor composed of atypical neoplastic, often pleomorphic cells that invade other tissues. "To explore the genomic mechanisms underlying CCT4 dysregulation in cancer, we first assessed its somatic alteration frequency across cancer types using cBioPortal datasets." (PMID 41403933, 2025). "To elucidate the functional landscape of CCT4 at the proteomic level, we analyzed its protein interaction profile and pathway associations across cancers." (PMID 41403933, 2025). "Our pan-cancer multi-omics analysis identifies CCT4 as a candidate oncogenic factor associated with tumor progression and immune modulation, with compelling evidence in LUAD." (PMID 41403933, 2025). "In summary, these findings implicate CCT4 as a regulatory factor in cancer-associated proteomic signaling, functionally bridging protein homeostasis with major oncogenic pathways." (PMID 41403933, 2025). "These knowledge gaps hinder the understanding of whether CCT4 represents a generalizable hallmark of cancer cell proliferation or reflects a more context-specific role." (PMID 41403933, 2025). "CCT4 expression correlated positively with TMB in several cancers including LUAD, BRCA, LUSC, and STAD, as well as MSI in DLBC, HNSC, UCEC, and STAD." (PMID 41403933, 2025). "Multiple lines of evidence from our analysis and the literature point to CCT4 as a facilitator of cell cycle progression and genomic stability in cancer cells." (PMID 41403933, 2025). "Taken together, these results indicate that both genetic alterations (amplification, mutation) and epigenetic dysregulation (promoter hypomethylation) contribute to the aberrant overexpression of CCT4 in cancer." (PMID 41403933, 2025). "Several CCT subunits, such as CCT2, CCT3, CCT4, CCT5, CCT6A, and CCT7, have been implicated in cancer progression." (PMID 40867231, 2025). "Next, we analyzed the potential clinical significance of CCT4 in pan-cancer by using Cox regression and log-rank tests, including four clinical survival indicators: OS, DSS, DFI, and PFI." (PMID 41403933, 2025). "This consistently demonstrated high expression of CCT4 in various cancers, such as LUAD, LIHC, LUSC, BRCA, CHOL, ESCA, and GBM (P < 0.05)." (PMID 41403933, 2025). "Next, we conducted a pan-cancer spearman correlation analysis between CCT4 and proteomic signaling molecules from the TCPA dataset." (PMID 41403933, 2025). "CCT subunits are upregulated in cancer EVs, and CCT4 can serve as a regulator of vesicle trafficking." (PMID 40553562, 2025). "In summary, these findings identify CCT4 as a pan-cancer upregulated gene with notable expression and potential biological significance." (PMID 41403933, 2025). "It is conceivable that, in cancer cells, nuclear CCT4 helps fold or assemble specific regulators (e.g. transcription factors or cell-cycle machinery), thereby enhancing proliferative capacity and modulating immune-related gene expression." (PMID 41403933, 2025). "To systematically evaluate CCT4’s position in the cancer immunity cycle, we computed its correlation with 7 canonical steps using TIP data." (PMID 41403933, 2025). "Another group of chaperone genes, such as CCT6A, CCT4, TCP1, CCT5, PTGES3 and CCT7, were previously implicated in cancer cell proliferation and predicts poor prognosis in HCC36,37." (PMID 33431814, 2021). "In this way, MALAT1 influences proliferation, invasion and migration of cancer cells through regulation of multitudinous known downstream genes, including several metastasis-related genes (CCT4/CTHRC1/ROBO1/MIA2) and cell cycle control genes (p21/p27/B-MYB)." (PMID 31792655, 2020). "Additionally, male patients exhibited higher CCT4 expression compared to female patients in several cancers (such as LUAD and HNSC), suggesting sex-biased regulation." (PMID 41403933, 2025). "CCT4-high tumor cells were enriched for cell-cycle regulators, suggesting that CCT4 upregulation may endow cancer cells with enhanced proliferative capacity." (PMID 41403933, 2025).
cancer (continued). "In this study, we performed an integrative pan-cancer investigation of CCT4 across 33 tumor types, leveraging publicly available transcriptomic, proteomic, genomic, and immunologic datasets from The Cancer Genome Atlas (TCGA), Genotype-Tissue Expression (GTEx), and complementary repositories." (PMID 41403933, 2025). "It was found that CCT4 was inversely associated with CD8+ T cells, regulatory T cells (Tregs), and activated NK cells, while positively correlated with macrophages (especially M0 and M2) in various cancers." (PMID 41403933, 2025). "Overall, CCT4 may serve as a potential prognostic and proliferative biomarker and a promising predictor of treatment sensitivity in malignant tumors." (PMID 41403933, 2025). "Notably, CCT4 has been linked to the stabilization of oncogenic signaling proteins, for instance, inhibiting CCT4/TRiC can impede STAT3 maturation in cancer cells." (PMID 41403933, 2025). "Furthermore, mRNA expression of CCT4 in pan-cancer and corresponding normal tissues was assessed using the TCGA database." (PMID 41403933, 2025). "In conclusion, this study demonstrates that CCT4 is aberrantly expressed in multiple tumor types and may play a significant role in the diagnosis and prognosis of various cancers." (PMID 41403933, 2025). "Furthermore, tumor-normal comparison of promoter methylation (Δβ values) demonstrated consistent CCT4 hypomethylation in various cancers, including BLCA, COAD, LUAD, LUSC, and PRAD." (PMID 41403933, 2025). "Thus, the observed downregulation of the CCT4 is consistent with RTX’s potential anti-cancer role." (PMID 40137900, 2025). "The hub proteins, such as CCT4, EZR, and GAPDH, are known to be involved in critical pathways like neutrophil degranulation and sirtuin signaling, which are linked to the altered metabolic profiles and increased cancer stemness observed in neoadjuvant-treated PDAC." (PMID 40559993, 2025). "Collectively, these findings establish CCT4 as a marker of immune evasion in LUAD, characterized by reduced immune infiltration, functional paralysis of the cancer-immunity cycle, and upregulation of immunosuppressive signaling axes." (PMID 41403933, 2025). "Across pan-cancer, CCT4 expression was closely related to age, such as in READ, ESCA, LIHC, LUSC, age was negatively correlated with CCT4 expression, while in KICH, GBMLGG, etc., it was positively correlated." (PMID 41403933, 2025). "When CCT4 is activated, the ERBB signal pathway is inhibited, the apoptosis is enhanced, the expression of MMP3/9 is downregulated, and cancer cells’ invasion and metastasis ability is decreased." (PMID 37058032, 2023). "Some of the genes were reported as cancer-related genes, such as CCT2, CCT3, CCT4, CCT6A, CCT7, CCT8." (PMID 33897772, 2021). "Significant upregulation of TCP1, CCT2/3/5/6A/8 levels have been found in a variety of cancers, with CCT3/6A/8 the best studied in HCC, while there are few studies on CCT4/5/7." (PMID 34676169, 2021). "For DCIS tissues, compared with both DCIS cancer-adjacent and normal tissues, we detected four up-regulated (GAPDH, HSPA9, CCT4, and SCPEP1) and 48 down-regulated proteins (including KRT10, APOA1, ALDH1A1, and others) in DCIS tissues." (PMID 33194682, 2020). "Although emerging evidence suggests a potential involvement of CCT family members in tumorigenesis, the expression landscape, regulatory mechanisms, and biological relevance of CCT4 across human cancers have not been systematically explored." (PMID 41403933, 2025). "CCT4 overexpression has been revealed in cancer cells compared with normal tissue, and the lack of CCT4 was found to promote apoptosis of cancer cells." (PMID 40137900, 2025). "CCT4 expression was positively correlated with oncogenic proteins involved in cell proliferation and survival, including PCNA, Cyclin B1, FOXM1, across multiple cancer types." (PMID 41403933, 2025).
cancer (continued). "Furthermore, there were differences for CCT4 (P = 0.0123) and CCT7 (P = 0.09886) in the mRNA expression levels and patients’ N stage, a staging system developed by the American Joint Committee on Cancer to classify patients by the involvement of regional lymph nodes." (PMID 33313411, 2020).
tumor (15 papers, 2017 to 2025). "Beyond cell-intrinsic effects, our analysis provides evidence that CCT4 upregulation is linked to an immunosuppressive tumor microenvironment, suggesting a role in tumor–immune system interactions." (PMID 41403933, 2025). "To determine the clinical relevance of CCT4 across tumor types, we analyzed its association with clinicopathological parameters." (PMID 41403933, 2025). "High CCT4 levels were linked to reduced immune cell infiltration and diminished anti-tumor immune signaling, specifically manifested as increased Th2 cell infiltration and decreased Th1 and CD8+ T-cell signatures." (PMID 41403933, 2025). "While we discuss plausible mechanisms by which CCT4 influences tumor biology, our data cannot definitively prove that CCT4 causes a given phenotype (e.g., immune evasion or proliferation), only that it is strongly associated." (PMID 41403933, 2025). "As expected, CCT4 co-expresses with genes encoding other subunits of the CCT complex in tumor, and this is better detected by GRACE than by the standard method." (PMID 29259170, 2017). "In addition, we evaluated the diagnostic value of CCT4 by calculating the area under the ROC curve (AUC) of each tumor type respectively in the TCGA dataset and the TCGA-GTEX dataset." (PMID 41403933, 2025). "This cell-cycle support function of CCT4 may be one contributor to its association with aggressive tumor behavior." (PMID 41403933, 2025). "In summary, CCT4 appears to promote tumor cell proliferation by regulating cell cycle checkpoints and structural components of mitosis, echoing the cell-cycle facilitating roles observed for other CCT subunits (e.g. CCT8 in HCC)." (PMID 41403933, 2025). "We mitigated this by incorporating prior experimental knowledge (e.g., citing functional studies where CCT4 was perturbed), but validation of modulating CCT4 in tumor-bearing mice and observing immune response is needed to confirm causality." (PMID 41403933, 2025). "Tumor progression analysis further revealed that in some tumors, such as LUAD, LIHC, PAAD, KIRP, HNSC, and KICH, the CCT4 expression levels increased with higher tumor grades or advanced clinical stages." (PMID 41403933, 2025). "Our findings provide mechanistic insights into the role of CCT4 in shaping tumor biology and offer potential avenues for future biomarker development and therapeutic targeting." (PMID 41403933, 2025). "Spatial expression patterns visualized through anatomical diagrams further supported this trend, showing increased abundance of CCT4 in tumor tissues compared to matched normal samples." (PMID 41403933, 2025). "CCT4 was preferentially expressed in a subset of tumor epithelial cells, exhibiting a heterogeneous and spatially restricted enrichment pattern across the UMAP landscape." (PMID 41403933, 2025). "Additionally, CCT4 expression exhibits diverse associations with core elements such as immune cell infiltration, tumor microenvironment features, and multiple predictive indicators, suggesting it may influence tumor immunity in diverse ways." (PMID 41403933, 2025). "The results showed that CCT4 was significantly elevated in multiple tumor types, including LUAD, LIHC, LUSC, and HNSC, among others." (PMID 41403933, 2025). "CCT4 was found to be aberrantly upregulated across a majority of tumor types, particularly in LUAD, where elevated expression was associated with advanced stage and inferior survival outcomes." (PMID 41403933, 2025). "In sum, the evidence to date supports a model in which CCT4 serves as a crucial node linking tumor proteostasis and immune evasion." (PMID 41403933, 2025). "CCT4 is a subunit of CCT, and knockdown of CCT4 has been shown to induce apoptosis of tumor cells, impaired organ development, and even lethality in Drosophila." (PMID 37143143, 2023). "Introduction of CCT4 or mLST8 into YB-1–knockdown cells partially rescued in vivo tumor cell growth and the intratumoral activity of both mTOR1 and mTOR2 signaling." (PMID 35239512, 2022).
tumor (continued). "The expression levels of CCT4 and CCT7 demonstrated to be significantly associated with the tumor stage of HNSC, and only CCT4 was related to patients’ N stage." (PMID 33313411, 2020). "For one of these (CCT4 from the KADA tumor), we were able to show recognition by the autologous TIL and expansion of specific T cells from patient peripheral blood." (PMID 31921104, 2019). "Through this comprehensive approach, our aim is to clarify whether CCT4 merely reflects the general requirement for proteostasis in rapidly growing tumors or if it plays a unique role in modulating tumor-immune dynamics in LUAD." (PMID 41403933, 2025). "The chaperonin TRiC/CCT complex, which mediates the folding of cytoskeletal and signaling proteins, has been associated with oncogenesis; however, the specific role of its subunit CCT4 in tumor–immune interactions remain unclear." (PMID 41403933, 2025). "These trends were consistent across multiple tumor types, indicating that CCT4 may contribute to oncogenic rewiring through the potentiation of proliferative and survival circuits." (PMID 41403933, 2025). "This suggests that CCT4-positive proliferative programs may actively participate in tumor–stroma crosstalk to support LUAD progression." (PMID 41403933, 2025). "Further dissection of these mechanisms, for instance by perturbing CCT4 in vivo, will be critical to determine whether targeting this chaperonin can reverse Th2-dominated immune escape and reinvigorate anti-tumor immunity in LUAD." (PMID 41403933, 2025). "CCT4 has been reported to regulate tumor cell growth and apoptosis as well as organ development." (PMID 37143143, 2023). "The expression levels of CCT4/7 were correlated with advanced tumor stage." (PMID 33313411, 2020). "Importantly, spatial mapping of CCT4 expression revealed a striking co-localization with the cnmf_3-enriched region, suggesting that CCT4 may act as a functional marker of this proliferative tumor cell state." (PMID 41403933, 2025). "To further determine whether the upregulation of CCT4 in tumor cells reflects a global activation of the TRiC complex or exhibits subunit-specific expression patterns, we systematically analyzed the expression profiles of all eight CCT family subunits (TCP1, CCT2–CCT8) at the single-cell level." (PMID 41403933, 2025). "Notably, CCT4 also correlated positively with most tumor ploidy, further implicating it as a marker of genomic disorder that may influence immune editing or escape." (PMID 41403933, 2025). "However, CCT4 also exhibited unique upregulation in specific tumor cell states." (PMID 41403933, 2025). "Different ATP-binding affinities for CCT subunits indicate that the chaperonin may function under a range of ATP concentrations, such as the nutrient-deprived tumor environment; however, findings on the role of CCT4 as an ATP sensor highlight the complex regulation of the ATPase cycle." (PMID 35602608, 2022). "The overall patterns were consistent with that of CCT4, suggesting that members of the CCT family are generally involved in shaping an immunosuppressive tumor microenvironment." (PMID 41403933, 2025). "To further delineate the immunological role of CCT4 in LUAD, we performed tumor immune microenvironment (TIME) profiling using a consensus of multiple deconvolution algorithms." (PMID 41403933, 2025). "According to GSE32863 sequencing data, increased expression of CCT3, CCT4, CCT5, CCT6A, CCT7, and CCT8 was observed in LUAD tumor tissues compared with paired normal tissues." (PMID 39259093, 2024). "Using TCGA data and immune deconvolution methods, we found that all LUAD samples in the top tier of CCT4 expression had significantly greater Th2 cell infiltration than those with low CCT4, whereas key anti-tumor immune effectors (Th1 and CD8+ T cells) were less in many high-CCT4 tumors." (PMID 41403933, 2025).
tumor (continued). "Reintroduction of CCT4 or mLST8 expression in YB-1–knockdown GSCWL1 and GSC456 cells reactivated mTOR signaling and partially rescued cell proliferation, tumor-sphere formation, and GSC self-renewal." (PMID 35239512, 2022). "Data from the UALCAN database indicated that CCT4, CCT5, CCT6A, and CCT8 exhibited significantly higher promoter methylation in normal tissues than in tumor tissues, suggesting that low promoter methylation may be responsible for upregulating these CCTs in LUAD." (PMID 39259093, 2024).
neurological diseases (2 papers, 2021 to 2026). "They include characteristic genes, Prnp, Cct4, Vegfd (Figf), Map9 (Mtap9), Pik3cg, Zfand5, Endog, and Hbq1, which are reportedly associated with AD, CJD, and/or related neurological disorders." (PMID 34959983, 2021).
cardiovascular disease (1 paper, 2023). "CCT4 is a subunit of TRiC that has been implicated in cell proliferation, apoptosis and organ development, but the effect of CCT4 on cardiovascular disease remains unclear." (PMID 37143143, 2023).
CCT4 also shares sentences with these, for which no sentence is quoted: adenoma (1 paper); Alzheimer disease (1); blastoma (1); endometrial cancer (1); fibrosarcoma (1); fungal infections (1); gastric tumors (1); head and neck squamous cell carcinoma (1); Hodgkins lymphoma (1); Infertility (1); kidney disease (1); liver cancer (1); lymph node metastasis (1); metabolic syndrome (1); myeloma (1); non-Hodgkin lymphoma (1); ovarian tumors (1); pancreatic cancer (1); papillary carcinoma (1); peripheral neuropathy (1); prostate carcinoma (1); pseudoexfoliation glaucoma (1); rectal cancer (1); squamous cell carcinoma (1); thyroid (1); thyroid cancer (1); thyroid tumor (1); transitional cell carcinoma (1).